INS (insulin)
Diseases named in the same sentence as INS in open-access papers (continued):
Sharing a sentence is not in itself a finding about the gene and the disease.
Hyperglycemia (continued). "However, although benefits of managing hyperglycemia such as intensive insulin therapy have been reported, the risk of hypoglycemia-related events should not be neglected." (PMID 39269943, 2024). "The Gene Set Enrichment Analysis suggests that CCS1, CCS3, and CCS5 are associated with glucose, insulin, and hypoxia metabolism, offering some insights into the previously observed correlations between metabolic markers such as stress‐induced hyperglycemia and recurrence." (PMID 38420847, 2024). "The insulin signaling pathway allows for the regulation of glucose transport or glycogen synthesis, and mistakes in this way can lead to decreased insulin transport and glucose uptake, which may cause hyperglycemia." (PMID 38612580, 2024). "Furthermore, recent studies have found that persistent hyperglycemia causes ER stress, which deteriorates the quality of secretory proteins like pro-insulin, which further plays a role in the pathogenesis of DM." (PMID 38778421, 2024). "T2DM, characterized by hyperglycemia, is triggered by IR and deficiency in insulin secretion." (PMID 39334959, 2024). "Importantly, fasting blood glucose levels were measured 10 min before insulin administration to account for hyperglycemia associated with mouse handling (time: 10)." (PMID 38960128, 2024). "Hence, PI3K/Akt inhibition blocks insulin-driven glucose uptake, resulting in a dose-dependent increase in plasma levels of fasting C-peptide and insulin, thus causing hyperglycemia." (PMID 38319732, 2024). "Second, remission benefits may occur through the diverse physiological effects of extensive weight loss, including reductions in hyperglycaemia, BP, insulin resistance, inflammation and hepatic fat levels." (PMID 38233592, 2024). "Furthermore, specific disruption of the muscle clock resulted in diminished insulin sensitivity in the muscle, causing hyperglycemia in the non‐fasting condition and glucose intolerance." (PMID 38294260, 2024). "Therefore, the impact of insulin therapy on the TyG index and IR depends on the overall net effect, which is associated with factors such as disease duration, degree of hyperglycemia, and duration of treatment." (PMID 39003471, 2024). "The study group concluded that MDG appeared to be more effective than a 50% reduction in insulin basal rate for the prevention of exercise-induced hypoglycemia and may cause less post- exercise hyperglycemia than oral glucose." (PMID 39944479, 2024). "Then, hyperglycemia triggers the production of more insulin, causing profound hyperinsulinemia." (PMID 39119412, 2024). "While the complete pathophysiology of DM remains under investigation, the typical underlying cause of hyperglycemia in mammals involves three key defects: impaired insulin sensitivity in peripheral tissues, increased hepatic gluconeogenesis, and compromized insulin secretion." (PMID 39269256, 2024). "It destroys insulin-producing pancreatic β cells by DNA fragmentation through alkylation and alteration of macromolecules; thereby, causing insulin-dependent like diabetic conditions like hypoinsulinemia and hyperglycemia." (PMID 38444587, 2024). "They argued that DM can lead to an increased incidence of LBP based on the following mechanisms: Type 1 DM, which is caused by reduced insulin secretion as a result of damage to pancreatic beta cells, creates an environment of chronic hyperglycemia and IL-1 beta stress." (PMID 38201008, 2024). "At some point, monitoring will reveal a person with persistent and/or recurrent hyperglycaemia prompting a decision on whether to start insulin, along with associated education and support for affected individuals and their families." (PMID 38910151, 2024). "Obesity also increases the risk of insulin resistance, characterised by cellular insensitivity to insulin, and is associated with a cluster of conditions, including hypertension, hyperglycaemia, central adiposity, and dyslipidaemia, known as metabolic syndrome." (PMID 39251829, 2024).
Hyperglycemia (continued). "We were not able to obtain reliable data for rapid‐acting insulin doses to be able to assess whether there was an association between bolus doses of rapid‐acting insulin for hyperglycemia and subsequent hypoglycemia, but this is a plausible mechanism." (PMID 39136541, 2024). "Notably, preclinical research has shown that the insulin feedback causing hyperglycaemia can be prevented using dietary or pharmaceutical approaches, which greatly enhance the efficacy of treatment." (PMID 39251829, 2024). "This deficiency or ineffectiveness of insulin results in hyperglycemia, anion-gap metabolic acidosis, ketosis, and electrolyte disturbances, which causes fatty acids to be released from adipose, leading to ketone production of both acetoacetate and β-hydroxybutyrate." (PMID 39360087, 2024). "That condition could probably be related to SARS-CoV-2, which mainly affects pancreatic islets, harms insulin secretion, and causes further deterioration of hyperglycemia and acute diabetes." (PMID 39118799, 2024). "Brain hyperglycaemia in PD might be closely associated with insulin depletion, malfunction in glucose metabolism, or perhaps the inability of cerebral insulin to cope with the pathological elevation of glucose." (PMID 39767747, 2024). "In addition, oxidative stress can cause hyperglycemia by stimulating the sympathetic nervous system and the hypothalamic–pituitary–adrenal axis, leading to insulin resistance." (PMID 38902690, 2024). "This high proportion of macrosomia can be explained by maternal hyperglycemia leading to the passage of higher levels of blood glucose (through the placenta) into fetal circulation, which causes fetal hyperglycemia that prematurely stimulate fetal insulin secretion." (PMID 38685068, 2024). "Furthermore, hyperglycemia caused by mTOR inhibitors can also result from reduced insulin secretion." (PMID 39410536, 2024). "A reduced expression of GIP receptors and/or a reduction in beta-cell mass and functional insulin secretory capacity are suggested as possible underlying mechanisms, maybe triggered by glucotoxicity/hyperglycemia." (PMID 39049087, 2024). "Thus, in PNDM patients, persistent hyperglycemia is caused by loss of pancreatic β-cell membrane excitability to glucose and loss of pancreatic insulin." (PMID 38791571, 2024). "Indeed, studies have worked to find that adrenomedullin and exosomes derived from PDAC cause paraneoplastic dysfunction of human beta-cells and suppress insulin secretion thereby causing hyperglycemia." (PMID 39200119, 2024). "These abnormally present cytokines inhibit insulin signalling in hepatocytes, resulting in impaired suppression of gluconeogenesis causing hyperglycaemia, which then leads to an increased production of very low-density lipoprotein and C-reactive protein levels." (PMID 38202263, 2024). "In addition to hyperglycemia caused by the dysfunction of pancreatic beta-cells that secrete insulin and to insulin resistance of metabolic tissues, the disease is associated with chronic hyperlipidemia." (PMID 38950680, 2024). "IR results in insufficient cellular response to insulin, causing hyperglycemia (HG)." (PMID 38791447, 2024). "However, chronic increased insulin secretion leads to pancreatic β-cell dysfunction and insulin deficiency, which eventually leading to the redevelopment of hyperglycemia, and ultimately T2D." (PMID 39165284, 2024). "Delayed rapid insulin injection before dinner is frequent and causes hyperglycemia overnight." (PMID 39062173, 2024). "Fetuses carrying a GCK mutation can derive benefit from moderate maternal hyperglycemia, stimulating insulin secretion in fetal islets, whereas this may cause macrosomia in wild-type fetuses." (PMID 38745742, 2024). "However, as disease progresses hyperglycaemia damages capillary structure which decreases beta cell capillary contact area and leads to a consequent reduction in insulin secretion, further accelerating loss of glucose homeostasis." (PMID 38814445, 2024).
Hyperglycemia (continued). "Corticosteroids reduces insulin sensitivity which may cause aggravating hyperglycemia, and chemotherapeutic agents, such as L-asparginase, directly inhibits insulin release." (PMID 39020360, 2024). "Some studies have reported increased blood glucose levels in COVID-19 patients, and this hyperglycemia may have been linked to impaired insulin signaling and glucose uptake." (PMID 38727305, 2024). "In patients with DM, ATP deficiency will inhibit insulin secretion and cause hyperglycemia." (PMID 39091901, 2024). "Notably, short-term, high-dose carbohydrate administration significantly burdens the liver, leading to elevated liver enzyme levels, pronounced hyperglycemia and insulin secretion, and a risk of hypoglycemia and refeeding syndrome due to excess insulin." (PMID 38702806, 2024). "Therefore, glucose levels rise, causing a greater release of insulin as compensation, which can wear down the pancreas, causing that over time, the body produces less and less insulin and further increases hyperglycemia levels." (PMID 39456742, 2024). "However, hyperglycemia during pregnancy is associated with increased oxidative stress, which impairs the insulin-dependent glucose uptake and increases apoptosis and placental dysfunction." (PMID 38792489, 2024). "We hypothesize that intraoperative hyperglycemia may be, at least partially, attributable to insulin loss due to adhesion on artificial surfaces and/or degradation by hemolysis." (PMID 38861464, 2024). "People with high carbohydrate intake or genetic susceptibility to impaired insulin secretion may have higher postprandial hyperglycemia prevalence." (PMID 39768789, 2024). "DM is a chronic hyperglycemia condition caused by impairment in insulin secretion, response to insulin, or both alterations, and is diagnosed by randomly measured glycemia ≥ 200 mg/dL, fasting glycemia ≥ 126 mg/dL, glycemic levels ≥ 200 mg/dL after a 2 h OGTT, and HbA1c ≥ 6.5%." (PMID 38667278, 2024). "However, type 2 diabetes differs from type 1 because patients make insulin but fail to respond adequately due to β-cell resistance or deficiency alongside glucotoxicity following sustained hyperglycemia." (PMID 39371721, 2024). "Therefore, ATP can be used as a biomarker of DM, providing information on hyperglycemia occurring due to impaired insulin secretion caused by genetic disorders." (PMID 39091901, 2024). "T2DM is characterized by defective insulin secretion by pancreatic β cells and tissue resistance to insulin responses, causing hyperglycemia, hyperinsulinemia, increased reactive oxygen species (ROS), oxidative stress, and adipose tissue hypertrophy, among other metabolic changes." (PMID 38892601, 2024). "The ongoing demands of monitoring blood glucose and administering insulin, as well as the associated risks of hypoglycemia, hyperglycemia, and potential chronic complications, pose substantial challenges that may disrupt routine daily activities." (PMID 38397323, 2024). "In summary, we show here that selective ablation of pancreatic beta-cell IL-22ra1 signaling leads to age-related hyperglycaemia associated with compromised insulin biosynthesis, reduced islet proliferation, increased islet cellular stress, inflammation, and MHC-II expression." (PMID 38811550, 2024). "Therefore, this study aims to examine the association between insulin use and cardiovascular effects in type-2 DM patients with uncontrolled hyperglycemia." (PMID 39295783, 2024). "Additionally, hyperglycemia and deficient insulin signaling at the glomerular compartment leads to deficient nucleoside uptake by the cells, consequently leading to chronically elevated extracellular adenosine levels." (PMID 38786068, 2024).
Hyperglycemia (continued). "As a metabolic disease, the occurrence of DPN has been suggested to be related to the imbalance of metabolic pathways caused by hyperglycemia, lipid metabolism disorders, and insulin abnormalities, which can lead to OS, inflammatory reaction, mitochondrial dysfunction, and nerve cell damage." (PMID 39072278, 2024). "Importantly, cellular senescence is a hallmark of T2DM, driven primarily by hyperglycemia and contributing to both compromised cellular responsiveness to insulin signaling and inadequate insulin production by pancreatic β-cells." (PMID 38930033, 2024). "Because both pathogenic states cause hyperglycaemia, the need for insulin rises." (PMID 38654804, 2024). "Thus, insulin deficiency is also likely to explain the association between hyperglycaemia and increased insulin clearance in CF." (PMID 39093413, 2024). "Therefore, slowing glucose absorption is important to normalize the pancreatic insulin response and mitigate postprandial hyperglycemia, a condition strongly associated with cardiovascular mortality." (PMID 38930808, 2024). "Since Alx3-deficient mice fed with a SCD are known to exhibit hyperglycemia and glucose intolerance, we assessed whether disparities in adiposity relative to control animals differentially affect insulin sensitivity." (PMID 39129011, 2024). "The conditional deletion of PITPNA in mice causes hyperglycemia and compromised insulin processing." (PMID 39057094, 2024). "This synergistic effect might be explained by the insulin-sensitizing effect of acarbose could neutralize the hyperglycemia condition caused by rapamycin." (PMID 38966557, 2024). "It is thought that alpha-2 agonists may cause a hyperglycemia resulting in a hyperkalemia, by inhibiting the release of insulin from pancreatic beta cells." (PMID 39544913, 2024). "Insulin usage and hyperglycemia were linked to a rise in both severe and less severe ROP." (PMID 38618439, 2024). "Conversely, insulin is the most potent in controlling hyperglycemia but carries a higher risk of hypoglycemia and weight gain, which may limit its use in certain populations." (PMID 39723311, 2024). "It is challenging for patients to self-monitor their blood glucose using fingerstick testing four to six times a day; however, this is especially important for women who are on multiple daily insulin injections to balance the risk of hyperglycaemia and hypoglycaemia." (PMID 37022834, 2024). "Similarly, Substance P participates in the regulation of glucose metabolism via insulin signaling-associated pathways, and in rats its intravenous administration leads to hypoinsulinemia, hyperglucagonemia, and subsequently to hyperglycemia." (PMID 39744637, 2024). "The characteristic of the postpartum AGM in Asian GDM women was higher post- glucose challenge levels.We know that postprandial hyperglycemia is mainly associated with reduced glucose uptake (mainly representing muscle) combined with glucose-stimulated insulin secretion dysfunction." (PMID 37432359, 2023). "In particular, L-asparaginase, a cytotoxic chemotherapeutic agent, has a direct toxic effect on pancreatic beta cells through the inhibition of insulin production and release, and an indirect contribution to hyperglycemia is associated with the development of pancreatitis." (PMID 36831436, 2023). "Therefore, the incidence of hypoglycemia is a very important safety indicator when assessing different insulin infusion modalities in the treatment of TPN-associated hyperglycemia." (PMID 37674887, 2023). "In animal models, as well as in in vitro studies with cultured podocytes, insulin has been shown to increase the permeability of the glomerular barrier to albumin, and insulin-resistant podocytes due to, for example, hyperglycemia or hyperinsulinemia are associated with albuminuria." (PMID 37760939, 2023).
Hyperglycemia (continued). "To examine further the role of adipose HK2 in glucose homeostasis, and in particular the causality of HK2 loss in insulin insensitivity and hyperglycemia, we generated an adipose-specific Hk2 knockout (AdHk2KO) mouse in which the knockout was induced at 4–5 weeks of age." (PMID 36920797, 2023). "When the fetus has not inherited the maternal GCK variant, treatment of maternal hyperglycaemia with insulin may reduce the risk of the baby being LGA." (PMID 37653058, 2023). "Interestingly, low-dose streptozotocin (STZ), which depletes insulin, causing hyperglycaemia due to β-cell destruction, failed to block lipid-driven mTORC1 (P-S6Ser235/236), mTORC2 (P-AKTSer473) and AKT (P-AKTThr308) activation." (PMID 37386153, 2023). "We were not surprised to find that the proteome and phosphoproteome of EV-enriched preparations were associated with hyperglycemia, insulin treatment and glucose variability as these are key drivers of T1D pathophysiology, but also with T1D pathogenic mechanisms." (PMID 37576973, 2023). "Hyperglycemia may be due to a relative or absolute deficiency of insulin and/or insulin resistance associated with disruptions in carbohydrate, lipid, and protein metabolism." (PMID 37371552, 2023). "In conclusion, lower SHBG levels in early pregnancy were associated with an increased risk for GDM, especially early‐onset disease, higher fasting glucose, and insulin treatment for fasting hyperglycaemia, whereas high T and FAI levels were associated with higher post‐prandial glucose values." (PMID 36484476, 2023). "In addition, IL-1R antagonists can reduce islet inflammation caused by hyperglycemia, thereby improving islet β-cell dysfunction, alleviating insulin resistance and blood sugar homeostasis." (PMID 38273819, 2023). "We hypothesized that hyperglycaemia related to donor insulin use in DBDs organ donors is largely caused by beta‐cell death." (PMID 37646197, 2023). "However, in type 1 diabetes, the insulin-secretory function of β-cells markedly deteriorates, leading to insulin deficiency and the resulting hyperglycemia." (PMID 38203600, 2023). "Hypothyroidism in a patient with T1DM may be accompanied by hypoglycemia due to reduced insulin requirements and increased insulin sensitivity, whereas hyperthyroidism is associated with hyperglycemia and higher insulin need." (PMID 36980146, 2023). "This could be associated with the expression of preptin together with insulin from the pancreas, secondary to hyperglycemia." (PMID 37434133, 2023). "In addition, promotion of LRP5 expression increased bone mass and bone strength in insulin-deficient diabetic mice, delaying the onset of hyperglycemia in these mice." (PMID 37106471, 2023). "This, in turn, suggested that the hyperglycemia caused by T2D itself might have an independent and secondary consequence of further impairing the ability of beta cells to synthesize and secrete insulin." (PMID 36834496, 2023). "However, our findings are comparable with the results of previous studies that assessed the association of dietary insulin indices and risk of cardiometabolic abnormalities, including dyslipidemia, hyperglycemia, IR, and adiposity." (PMID 37069259, 2023). "Hyperglycemia is mainly caused by increased insulin resistance." (PMID 37432173, 2023). "The reduced serum insulin levels may be due to the progressive damage of the pancreatic β‐cells caused by persistent hyperglycemia in db/db mice." (PMID 37051358, 2023). "Insulin underdosing or skipping insulin is associated with recurrent episodes of diabetic ketoacidosis, severe hyperglycemia episodes, poor metabolic control, and the development of macro and micro complications, dramatically increasing morbidity and mortality." (PMID 37665472, 2023). "Plasma insulin levels were also positively associated with GC compared with hyperglycemia." (PMID 38020199, 2023).